RN7SL495P (RNA, 7SL, cytoplasmic 495, pseudogene)
Gene: Miscellaneous RNA gene on chromosome 15 (22,609,141 to 22,609,377, reverse strand). Ensembl gene ENSG00000277515.
Homologues: Orthologues: chimpanzee Metazoa_SRP (99% identical), pig Metazoa_SRP (59% identical). Paralogues in human: RN7SL469P (99% identical), RN7SL673P (99% identical), RN7SL628P (99% identical), RN7SL719P (99% identical), RN7SL82P (99% identical), RN7SL185P (97% identical), RN7SL196P (97% identical), RN7SL286P (97% identical), RN7SL539P (97% identical), RN7SL796P (96% identical), Metazoa_SRP (92% identical), RN7SL106P (92% identical), and 708 more.